NCALD (neurocalcin delta)
Description:
May be involved in the calcium-dependent regulation of rhodopsin phosphorylation. Binds three calcium ions.
Tractability: PROTAC: ubiquitination databases record sites on it; its protein half-life has been measured.
Gene: Protein-coding gene on chromosome 8 (101,686,542 to 102,124,907, reverse strand). Ensembl gene ENSG00000104490.
Pathways (Reactome):
Neuronal System: Activation of Ca-permeable Kainate Receptor
Gene Ontology:
Molecular function: actin binding; clathrin binding; protein binding; tubulin binding; calcium ion binding; alpha-tubulin binding
Biological process: calcium-mediated signaling; regulation of signal transduction; vesicle-mediated transport
Cellular component: clathrin coat of trans-Golgi network vesicle; cytosol
Genetic constraint (gnomAD): Loss-of-function variants: 8 observed, 16.52 expected, observed/expected ratio (o/e) 0.48, 90% interval 0.28 to 0.87. The upper end of that interval is the gene's LOEUF score, 0.87, which puts it in group 3 of 6, group 1 being the genes least tolerant of losing a copy. Missense variants: 177 observed, 251.29 expected, observed/expected ratio (o/e) 0.7, 90% interval 0.62 to 0.8. Synonymous variants: 87 observed, 91 expected, observed/expected ratio (o/e) 0.96, 90% interval 0.8 to 1.14.
Homologues: Orthologues: chimpanzee NCALD (100% identical), dog NCALD (100% identical), guinea pig NCALD (100% identical), mouse Ncald (100% identical), pig NCALD (100% identical), rat Ncald (100% identical), tropical clawed frog ncald (99% identical), zebrafish ncalda (98% identical), Drosophila melanogaster Nca (87% identical), macaque NCALD (84% identical), rabbit NCALD (84% identical). Paralogues in human: HPCAL1 (91% identical), HPCA (88% identical), VSNL1 (67% identical), HPCAL4 (64% identical), NCS1 (58% identical), RCVRN (49% identical), GUCA1B (45% identical), KCNIP2 (42% identical), KCNIP1 (39% identical), KCNIP3 (39% identical), KCNIP4 (39% identical), GUCA1A (38% identical), and 2 more.